UBL4A (ubiquitin like 4A)
Description:
As part of a cytosolic protein quality control complex, the BAG6/BAT3 complex, maintains misfolded and hydrophobic patches-containing proteins in a soluble state and participates in their proper delivery to the endoplasmic reticulum or alternatively can promote their sorting to the proteasome where they undergo degradation. The BAG6/BAT3 complex is involved in the post-translational delivery of tail-anchored/type II transmembrane proteins to the endoplasmic reticulum membrane. Recruited to ribosomes, it interacts with the transmembrane region of newly synthesized tail-anchored proteins and together with SGTA and ASNA1 mediates their delivery to the endoplasmic reticulum. Client proteins that cannot be properly delivered to the endoplasmic reticulum are ubiquitinated and sorted to the proteasome. Similarly, the BAG6/BAT3 complex also functions as a sorting platform for proteins of the secretory pathway that are mislocalized to the cytosol either delivering them to the proteasome for degradation or to the endoplasmic reticulum. The BAG6/BAT3 complex also plays a role in the endoplasmic reticulum-associated degradation (ERAD), a quality control mechanism that eliminates unwanted proteins of the endoplasmic reticulum through their retrotranslocation to the cytosol and their targeting to the proteasome. It maintains these retrotranslocated proteins in an unfolded yet soluble state condition in the cytosol to ensure their proper delivery to the proteasome.
Synonyms: DXS254E; GDX; UBL4; GET5; MDY2; TMA24; DX254E
Tractability: Small molecule: a structure with a bound ligand is known. PROTAC: UniProt records ubiquitination sites on it; ubiquitination databases record sites on it; its protein half-life has been measured.
Gene: Protein-coding gene on chromosome X (154,483,717 to 154,486,615, reverse strand). Ensembl gene ENSG00000102178.
Subcellular location: Cytoplasm, cytosol; Nucleus
Subcellular location (Human Protein Atlas): Cytosol; Nucleoplasm
Pathways (Reactome):
Protein localization: Insertion of tail-anchored proteins into the endoplasmic reticulum membrane
Gene Ontology:
Molecular function: protein binding; protein-folding chaperone binding; ubiquitin-like protein transferase activity
Biological process: post-translational protein targeting to endoplasmic reticulum membrane; regulation of protein stability; tail-anchored membrane protein insertion into ER membrane; ubiquitin-dependent protein catabolic process; protein modification process
Cellular component: BAT3 complex; cytoplasm; cytosol; membrane; nucleoplasm; nucleus
Homologues: Orthologues: mouse Ubl4a (90% identical), chimpanzee UBL4A (89% identical), dog UBL4A (89% identical), guinea pig UBL4A (89% identical), rat Ubl4a (87% identical), zebrafish UBL4A (61% identical), tropical clawed frog ubl4a (55% identical). Paralogues in human: UBL4B (43% identical), ZFAND4 (27% identical), ISG15 (21% identical), ANKUB1 (20% identical), UBC (20% identical), RPS27A (20% identical), UBA52 (19% identical), UBD (17% identical), NEDD8 (13% identical), UBB (3% identical).
Diseases named in the same sentence as UBL4A in open-access papers:
UBL4A is named in the same sentence as 17 diseases in open-access papers, as found by Europe PMC text mining. Sharing a sentence is not in itself a finding about the gene and the disease. The quoted sentences say what the papers report.
pancreatic ductal adenocarcinoma (6 papers, 2019 to 2024). An infiltrating adenocarcinoma that arises from the epithelial cells of the pancreas. "This oncogenic autophagy is also observed in pancreatic ductal adenocarcinoma as suppression of autophagy through the direct interaction between ubiquitin-like protein 4A (UBL4A) and lysosome-associated membrane protein 1 (LAMP-1) inhibits pancreatic tumor migration and invasion." (PMID 33297435, 2020). "A study on pancreatic cancer demonstrated that ubiquitin-like protein UBL4A can modulate the proliferation and metastasis of pancreatic ductal adenocarcinoma (PDAC) through inhibition of autophagy." (PMID 39669571, 2024). "RAPH1, SOX14, DPEP1, and UBL4A have a significant role in the invasion or metastasis of breast cancer, cervical cancer, colon cancer, and pancreatic ductal adenocarcinoma, respectively." (PMID 37378426, 2023). "The underlying mechanism of the role that ubiquitin-like protein 4A (UBL4A) plays in autophagy-mediated metastasis by suppressing autophagy and disturbing lysosomal functions through targeting LAMP1 in pancreatic ductal adenocarcinoma was unveiled recently." (PMID 33430230, 2021). "In summary, these results demonstrate that UBL4A inhibits autophagy-mediated proliferation and metastasis of pancreatic ductal adenocarcinoma by directly targeting LAMP1." (PMID 31288830, 2019). "UBL4A inhibits metastasis of pancreatic ductal adenocarcinoma." (PMID 37378426, 2023). "Pancreatic ductal adenocarcinoma (PDAC) is still a major cause of cancer-related death and the underlying molecular mechanism of UBL4A and PDAC remains unknown." (PMID 31288830, 2019).
pancreatic cancer (2 papers, 2019 to 2024). "Together, these data indicate that UBL4A is a potent autophagic inhibitor that causes autophagosome accumulation due to impaired autophagic degradation and suppresses pancreatic cancer proliferation and metastasis by inhibiting autophagy." (PMID 31288830, 2019). "However, the underlying molecular mechanisms by which UBL4A regulates autophagy and contributes to pancreatic cancer development and progression remain unknown." (PMID 31288830, 2019). "Next, the effects of UBL4A on proliferation and metastasis in pancreatic cancer were evaluated by functional assays in vitro and in vivo." (PMID 31288830, 2019). "Together, these data indicate that LAMP1 restoration in pancreatic cancer cells reverses the UBL4A-induced antitumor effects and inhibition of autophagy." (PMID 31288830, 2019). "Nevertheless, our data indicate that UBL4A suppresses pancreatic cancer development by directly regulating LAMP1." (PMID 31288830, 2019). "The current data provide greater insights into the function of the UBL4A/LAMP1 autophagy axis in the aggressive progression of pancreatic cancer." (PMID 31288830, 2019). "Taken together, our data suggest that UBL4A inhibits tumor proliferation and metastasis in orthotopic pancreatic cancer models." (PMID 31288830, 2019). "Herein, we describe a novel mechanism of UBL4A that suppresses the progression of pancreatic cancer." (PMID 31288830, 2019). "Our findings suggest a new mechanism for the regulation of proliferation and metastasis by the UBL4A/LAMP1/autophagy axis in pancreatic cancer and reveal a direct interaction between UBL4A and LAMP1." (PMID 31288830, 2019). "Together, these results indicate that UBL4A inhibits tumor proliferation and metastasis in pancreatic cancer cells." (PMID 31288830, 2019). "Our findings demonstrate the valuable function of UBL4A, which may perform as a novel therapeutic target in the treatment of pancreatic cancer." (PMID 31288830, 2019). "Furthermore, UBL4A caused lysosomal dysfunction by directly interacting with LAMP1, and LAMP1 overexpression reversed the antitumor effects of UBL4A in pancreatic cancer." (PMID 31288830, 2019). "Moreover, increased expression of UBL4A caused increased levels of LAMP1, LC3B, p62, and E-cadherin and resulted in decreased levels of CTSB, vimentin, and N-cadherin in the orthotopic pancreatic cancer models." (PMID 31288830, 2019). "First, the prognostic role of UBL4A and its expression in human PDAC patients and in pancreatic cancer cell lines were detected by survival analysis and qRT-PCR, western blotting, and immunohistochemistry." (PMID 31288830, 2019). "Additionally, immunohistochemical results showed that the UBL4A level was positively correlated with the expression of LAMP1, LC3B, p62, and E-cadherin and negatively correlated with CTSB, vimentin, and N-cadherin in pancreatic cancer patients." (PMID 31288830, 2019). "However, in this study, we did not determine whether UBL4A regulates the expression of LAMP1through an exact mechanism, such as the ubiquitination–proteasome pathway, or which signaling pathways contribute to the UBL4A-induced antitumor effects in pancreatic cancers." (PMID 31288830, 2019).
Arthritis (1 paper, 2024). Inflammation of a joint. "UBL4A knockout mice resist collagen-induced arthritis by regulating the balance of Th1, Th17, and regulatory T cells in the T cell subpopulation." (PMID 38428406, 2024).
atherosclerosis (1 paper, 2022). A disease characterized by the build-up of fatty material and calcium deposition in the arterial wall resulting in partial or complete occlusion of the arterial lumen. "UBC and UBL4A, the two most connected hub genes of the network, belong to the ubiquitin family, whose members play a role in BAVs as well as in atherosclerosis." (PMID 35463757, 2022).
motor neuron disease (1 paper, 2025). "It is tempting to speculate that partial loss-of-function mutations or haplo-insufficiency in one or more of the human TRC pathway components (WRB, CAML, TRC40/ASNA1, TRC35, Ubl4A, Bag-6/Bat-3/Scythe) may in the future be found to be causative in inherited cases of ALS or other motor neuron disease." (PMID 39823474, 2025).
scoliosis (1 paper, 2024). A congenital or acquired spinal deformity characterized by lateral curvature of the spine. "UBL4A knockout mice showed mild kyphosis and scoliosis with dysregulation of osteoblastogenesis and chondrogenesis." (PMID 38428406, 2024).
Sepsis (1 paper, 2023). Sepsis is defined as life-threatening organ dysfunction caused by a dysregulated host response to infection. "A miR-34b-3p agomir injection ameliorated sepsis-induced mouse AKI via an anti-inflammatory mechanism by targeting ubiquitin-like protein 4A (UBL4A)." (PMID 37761260, 2023).
tumor (4 papers, 2019 to 2024). "Since USP1 is known to act in an oncogenic manner while UCHL1 and UBL4A are shown to have tumor-suppressive functions, we focused our studies on how USP1 alters TAZ." (PMID 33114077, 2020). "High UBL4A expression induced a small tumor size and reduced tumor weight in the orthotopic tumor model." (PMID 31288830, 2019). "In this study, we observed that UBL4A inhibited tumor proliferation and metastasis through the suppression of autophagy." (PMID 31288830, 2019). "In summary, our data highlight that UBL4A is a novel autophagy inhibitor and tumor suppressor in PDAC." (PMID 31288830, 2019). "Other known functions of UBL4A include involvement in tumor suppression and in cell death in response to DNA damage, indicating the versatile capabilities of this protein." (PMID 31288830, 2019). "A recent study has identified ubiquitin-like protein 4A (UBL4A), a tumor suppressor mediating cell death in response to DNA damage, and a protein folding chaperone, to directly interact with LAMP1." (PMID 31905604, 2019). "We observed that UBL4A inhibited tumor proliferation and metastasis through suppression of autophagy, a critical intracellular catabolic process that reportedly protects cells from nutrient starvation and other stress conditions." (PMID 31288830, 2019). "Consistently, CQ abolished the antitumor effects of UBL4A on tumor proliferation and metastasis in vitro." (PMID 31288830, 2019). "Next, CQ, which blocks late-stage autophagy, was used to examine the effects of UBL4A on autophagosome processes and the relationship between autophagy and tumor progression." (PMID 31288830, 2019). "Additionally, LAMP1 was identified as a direct target responsible for UBL4A-induced tumor suppression and autophagy inhibition." (PMID 39669571, 2024). "In addition, we demonstrate that LAMP1 is a direct target in UBL4A-induced tumor suppression and inhibition of autophagy." (PMID 31288830, 2019). "In addition, chloroquine was introduced to determine the role of autophagy in UBL4A-related tumor proliferation and metastasis." (PMID 31288830, 2019). "In addition, we demonstrated that UBL4A suppressed tumor growth and metastasis in a pancreatic orthotopic tumor model." (PMID 31288830, 2019). "In this study, we demonstrated that the elevated expression of UBL4A contributed to a favorable prognosis for PDAC patients and that UBL4A suppressed tumor growth and metastasis by inhibiting autophagy." (PMID 31288830, 2019). "Intriguingly, CQ eliminated the influence of UBL4A on autophagic flux but could not cooperate with UBL4A during the inhibition of tumor proliferation and metastasis, which indicated that UBL4A was a potent autophagic inhibitor that caused impaired autophagic degradation." (PMID 31288830, 2019). "Consistently, our data showed that CQ abolished the effects of UBL4A on autophagy inhibition and tumor suppression and had no synergetic function with UBL4A." (PMID 31288830, 2019).
cancer (3 papers, 2016 to 2022). A tumor composed of atypical neoplastic, often pleomorphic cells that invade other tissues. "Knockdown of LAMP1 reversed the UBL4A-induced autophagy suppression, mesenchymal-to-epithelial transition, inhibiton of autophagic flux, inhibition of cancer cell migration and invasion, cell proliferation and wound healing capacity." (PMID 31288830, 2019). "In cancer, UBL4A represses tumorigenesis and is involved in various signaling pathways." (PMID 31288830, 2019). "However, understanding of the exact biological function of UBL4A in the regulation of cancer cells, especially in PDAC, remains elusive." (PMID 31288830, 2019). "We identified the top five related genes (DKC1, FAM58A, NAA10, SLC10A3, UBL4A) that mostly correlated with IRAK1 by GEPIA2.0; the heatmap displayed the correlation in pan-cancers." (PMID 35669566, 2022).
immune dysfunction (1 paper, 2024). "UBL4A plays an important role in the development of immune dysfunction and subsequent abnormal bone metabolism." (PMID 38428406, 2024).
UBL4A also shares sentences with these, for which no sentence is quoted: breast carcinoma (1 paper); cervical cancer (1); cognitive decline (1); colon cancer (1); neurodegenerative disease (1); pancreatic (1); protein-misfolding diseases (1).